MMP9 (matrix metallopeptidase 9)
Diseases named in the same sentence as MMP9 in open-access papers (continued):
Sharing a sentence is not in itself a finding about the gene and the disease.
breast carcinoma (continued). "This study demonstrates an important link between BHMC and the invasiveness of MDA-MB-231 breast carcinoma cells by significantly inhibiting invadopodia formation and reducing invasion/invadopodia-related protein expressions such as β-PIX, MMP-9, and MT1-MMP." (PMID 29642589, 2018). "For example, mRNA levels of MMP-2 and its closely related MMP family member MMP-9 are significantly higher in MDA-MB-231 and MCF-7 breast cancer cell lines (MDA-MB-231 and MCF-7) compared to the normal HS578Bst cell line." (PMID 29874869, 2018). "By gain‐ and loss‐of‐function assays, we show that depletion of Furin in Plac1‐overexpressing breast cancer cells attenuated the Plac1‐induced expression of NICD, HES1, MMP2, and MMP9 and tumor cell invasion and metastasis." (PMID 29704427, 2018). "Taken together, we determined that IL-6, CCL2, MMP9, MMP2, and CHOP expression are all inversely correlated with IGF-1R expression in human breast cancer." (PMID 30458886, 2018). "The results of our study demonstrate that AREG increases intracellular MMP-9 and -2 levels both under control conditions and upon infection, which is consistent with a previous study that showed AREG to upregulate MMP-9 in breast cancer cells." (PMID 30524196, 2018). "MLK3 is essential for FRA-1 expression in breast cancer cells and raises MMP-1 and MMP-9 by FRA-1, which is important for breast cancer cell invasion and transendothelial migration." (PMID 29596304, 2018). "According to the literature, high metastatic lung cancer, rectal cancer and breast cancer are found to have high MMP-2 and MMP-9." (PMID 30558243, 2018). "Knock-down of CD44 decreased mRNA expression of MMP9, MMP14, and urokinase plasminogen activator (uPA) and inhibited cancer cell invasion in the basal-like human breast cancer cells." (PMID 29747682, 2018). "STAT3 phosphorylation and activation is known has been shown to enhance breast cancer migration through the induction of gene involved with EMT, such as SNAIL, MMP9 and TWIST and also induced autocrine secretion of IL-623,31,34." (PMID 29891854, 2018). "We developed a monoclonal antibody against murine MMP-9, which we found decreased growth of established primary tumors in an orthotopic model of HER2-driven breast cancer (HC11-NeuT) in immunocompetent mice." (PMID 30500835, 2018). "Within proteins that are differentially expressed in M1- and M2-like TAM subtypes, we were particularly interested in MMP-9, a member of MMP family, because it has been shown to play a role in extracellular matrix remodeling and invasion in breast cancer." (PMID 30558648, 2018). "Further investigation showed that fascin up-regulated NF-κ B activity, uPA, MMP-2 and MMP-9 expression, but down-regulated the expression and nuclear translocation of BRMS1, resulting in a higher ability of breast cancer cells to migrate and invade." (PMID 29285273, 2017). "Given that MMP9 is regulated by TGF-β and pro-inflammatory TNF/IL-1β cytokines, expression of these cytokines was also examined in human breast carcinomas." (PMID 28423685, 2017). "Obviously, we found an elevated expression of MMP-2 and MMP-9 in MCF-7, A549 and H1793, while MMP-1 expression was only observed in breast cancer cell line." (PMID 28915603, 2017). "In agreement with our results HDAC1 siRNA inhibited invasion by decreasing MMP9 mRNA expression, while overexpression of HDAC1 increased invasion and MMP9 expression in breast cancer." (PMID 28624794, 2017). "Our data show that SID peptide downregulates Wnt/β-catenin reporter activity and direct Wnt target genes (LEF1, TCF7L2, CD44, PLAU, MT1-MMP, MMP9, HMGA2) involved in breast cancer invasion and metastasis." (PMID 29179446, 2017). "In this study, we demonstrated that β-lap up-regulated epithelial marker E-cadherin, and down-regulated Vimentin, twist, Slug, Snail, and MMP-9, which indicated that β-lap suppressed EMT progression in breast cancer cells." (PMID 28578385, 2017).
breast carcinoma (continued). "Recent studies in gastric carcinoma, breast cancer and chondrosarcoma cells exemplify the Src-FAK-mediated regulation of MMPs like MMP9 and MMP13 via activation of AP-1 transcription factors like c-Jun and c-Fos." (PMID 26001294, 2017). "In gastric cancer and breast cancer cells, inhibition of PI3K/AKT signaling pathway repressed MMP2/MMP9 activation and reduced EMT." (PMID 27880942, 2017). "Consistently, IF analysis also revealed that β-lap significantly increased E-cadherin expression and decreased the expressions of Vimentin and MMP-9 in the MCF-7 and MDA-MB-231 breast cancer cell lines." (PMID 28578385, 2017). "Their study suggests that in the presence of high MMP9 levels, IGFBP is digested, and then IGF is released and activates IGF signaling pathways that promote tumorigenesis in breast cancer." (PMID 28143425, 2017). "Resveratrol, a polyphenol naturally produced by many fruits, reduced growth factor heregulin-β1 (HRG-β1)-mediated MMP-9 expression, phosphorylation of ERK1/2 and invasion in MCF-7 breast cancer cells." (PMID 27999314, 2016). "EGCG and Green tea polyphenols (GTP) mediate epigenetic activation of TIMP-3 levels, resulting in suppression of invasiveness and gelatinolytic activity of MMP-2 and MMP-9 in MDA-MB-231 and MCF-7 breast cancer cells." (PMID 27999314, 2016). "Overexpression of WNT11 in EMSCs and BT-474 breast cancer cell lines resulted in higher MMP-2 and/or MMP-9 zymographic activities." (PMID 26861754, 2016). "Several MMPs have been reported to induce EMT, including MMP-3 in breast cancer, MMP-7 in gastric and lung cancer cell lines, MMP-9 in ovarian and squamous cancer cell lines, and MT1-MMP in an ischemic rat kidney cell line." (PMID 27374080, 2016). "Increased expression of Mmp9, a gene that is transcriptionally regulated by ETS family transcription factors, has been reported to promote breast cancer progression." (PMID 26752700, 2016). "After transfecting the breast cancer cells MDA-MB-231, T47D and ZR-75-1 with siRNA against uPA and MMP9, transcript levels have been checked in the respective cells." (PMID 26906973, 2016). "There are various RTKs and downstream proteins involved in breast cancer and metastasis such as VEGF, MMP9, GLUT1 and FOXM1." (PMID 26922065, 2016). "Further corroborating our findings, we found that mRNAs for CXCL16 as well as for IL8, CSF2, MMP9, EDN1 and CCL2 all were expressed at significantly higher levels in basal-like breast cancers as compared with luminal A tumours." (PMID 27725631, 2016). "In breast cancer, the invasive activity of PMA-induced MCF-7 cells was blocked by the flavonol by reducing MMP-9 expression and by blocking activation of the protein kinase C (PKC)/ERK/AP-1 signaling cascade." (PMID 27827912, 2016). "Given that miR-204 decreases cellular levels of Rab40b in breast cancer cells, miR-204 would also be expected to inhibit MMP2 and MMP9 targeting to the forming invadopodia." (PMID 27789576, 2016). "Nobiletin exerts antimetastatic effects on human breast cancer cells through the down-regulation of both CXC chemokine receptor type 4 (CXCR4) and MMP-9 via a mechanism involving NF-κB inhibition and MAPKs activation." (PMID 27827912, 2016). "Highlighted Article: Rab40b plays a key role in mediating invadopodia function during breast cancer cell invasion by binding to Tks5 and functioning as a tether mediating MMP2 and MMP9 targeting to the extending invadopodia." (PMID 27789576, 2016). "AGPAT9 inhibits breast cancer invasion through, at least in part, up-regulating the activities of MMP-2 and MMP-9." (PMID 26110566, 2015). "MMP-2 and MMP-9 are complex members of the MMP family and demonstrate upregulated expression in breast cancer." (PMID 26599012, 2015). "This evidence reveals that PRMT7 is capable of inducing MMP9 expression, representing a mechanism through which PRMT7 can promote breast cancer cell invasion." (PMID 25605249, 2015).
breast carcinoma (continued). "We found that RGD-stimulation of metastatic breast cancer cells upregulated the expression of MMP-2 and MMP-9." (PMID 28721370, 2015). "MMP-9, as a member of MMP family, was reported to have higher expression in brain-selective breast cancer cells than that of parental and bone-selective cells." (PMID 26400100, 2015). "As a result, this meta-analysis focuses on effects of MMP-9 and MMP-2 expression on prognosis for breast cancer." (PMID 26270045, 2015). "Silencing KDM2A using small interfering RNAs increased the invasion and migration of breast cancer cells by suppressing a subset of matrix metalloproteinases, such as MMP-2, MMP-9, MMP-4 and MMP-15." (PMID 26430963, 2015). "Together, our current observations point to a potential oncogenic role for EpCAM in breast cancer cell invasion and migration, possibly via activation of the Ras/Raf/EFK pathway by MMP-9 upregulation through Fos and Jun." (PMID 26356670, 2015). "miR-33b can decrease the levels of MMP-2, MMP-9, LOX, CXCR4, FN and p-FAK in breast cancer cells by regulating downstream targets." (PMID 25919570, 2015). "Previous studies suggest that cordycepin inhibits MMP-2 and MMP-9 expression and suppresses MAPK/AP-1 and Akt/PI3K pathways in breast cancer and prostate carcinoma cells, suppressing cancer invasiveness." (PMID 25868853, 2015). "In the cell experiment, reduction of CHD1L inhibited the invasion and metastasis of breast cancer cells by mediating MMP-2 and MMP-9 expression." (PMID 26599012, 2015). "Expression of the double or triple mutants of RUNX2 in breast cancer cells reduces the mRNA levels of two metastasis-related target genes, MMP9 and MMP13, and reduces the RUNX2-dependent invasive potential of breast cancer cells." (PMID 26204939, 2015). "TIMP-1 is the tissue inhibitor of MMP-9, which negatively regulating MMP-9 enzyme activity were involved in several tumor metastasis processes, including breast cancer." (PMID 25888829, 2015). "In the present study, both fibroblast- and breast cancer-CM showed similar effects on macrophages, as both induced higher secretion levels of TNF-α and higher MMP-9 activity in LPS stimulated macrophages." (PMID 25588705, 2015). "In a co-culture study breast cancer cells induced NO production by macrophages, which promoted cancer cell invasion favouring VEGF-A and MMP-9 expression." (PMID 25588705, 2015). "Matrix metalloproteinase 9 (MMP9) and Matrix metalloproteinase 2(MMP2) show a stronger expression in breast cancer tissue compared to that in normal breast tissue." (PMID 26674531, 2015). "Consistent with their report, our study indicated that the upregulation and activation of MMP-9 via the Ras/Raf/ERK signaling pathway was required for EpCAM-mediated growth and invasion of breast cancer cells." (PMID 26356670, 2015). "Most importantly, immunohistochemical staining of human breast cancer samples strongly showed that the coexpression of TSP50 and p65 as well as TSP50 and MMP9 were correlated with increased metastasis and poor survival." (PMID 25811800, 2015). "High expression of MMP-2 (P=1.5e−6), MMP-9 (P=0.027), and MMP-14 (P=0.00051) is predictive of lower RFS in chemotherapy treated for ER− human breast cancer patients." (PMID 28721370, 2015). "In conclusion, our data show that knockdown of EpCAM can inhibition breast cancer cell growth and metastasis via inhibition of the Ras/Raf/ERK signaling pathway and MMP-9." (PMID 26356670, 2015). "In human breast cancer cells, nobiletin downregulated the constitutive expression of CXCR4 and MMP-9." (PMID 26131016, 2015). "Serum MMP-9 (P=0.0013), NO (P<0.0001), and CA 15-3 (P<0.0001) were significantly increased while serum TAC was significantly (P=0.01) decreased in breast cancer patients as compared to the control group." (PMID 24634847, 2014). "For example, in melanoma and breast carcinoma cells, apoptosis induced by TNF receptor ligands was clearly enhanced by inhibiting MMP-9 (or MMP-2)." (PMID 24956101, 2014).
breast carcinoma (continued). "Furthermore, neutrophil-derived gelatinase B/MMP-9 has been implicated in inflammation-associated lymphangiogenesis, promoting VEGF-A bioavailability and bioactivity and, together with VEGF-C, has been implicated in lymphangiogenesis and lymph node metastasis in breast cancer." (PMID 24473089, 2014). "Through combined detection of VEGF and MMP-9, the present study identified that the levels were correlated with TNM-staging, primary tumor size and lymph node metastasis in breast cancer." (PMID 24944618, 2014). "Expression of some MMPs correlated with FOXC1 expression, such as MMP7 in breast cancer and MMP1, MMP2, MMP7, and MMP9 in hepatocellular cancer." (PMID 24889262, 2014). "However, the value of combined detection of VEGF and MMP-9 levels in breast cancer remains unclear." (PMID 24944618, 2014). "On the other hand, elevated levels of MMP-9 expression were detected in the stroma surrounding cancer cells in both triple-negative and HER2-positive breast cancer." (PMID 25151367, 2014). "In MCF7 human breast cancer cells, stable expression of an active STAT3 increased MMP-9 mRNA levels as well as transcriptional activation of the MMP-9 gene." (PMID 24743777, 2014). "The antimetastatic effect of BBR is evidenced from reduced expressions of MMP-9, which is in agreement with previous studies demonstrating the antimetastatic effects of BBR in breast cancer models." (PMID 24614362, 2014). "The construction of in vivo models of breast cancer metastasis to the bone further confirmed the inhibition of bone metastasis as a result of CXCR4 interference and the involvement of CXCR4/PI3K/AKT/MMP-9 signaling in bone metastasis." (PMID 24959222, 2014). "In mice transgenic for the gelatinase B/MMP-9 inhibitor TIMP-1, paradoxical effects have been described, with high circulating TIMP-1 inhibiting DMBA-induced mammary tumour growth, blocking tumorigenesis at an early stage." (PMID 24473089, 2014). "In this report we provide novel data showing that macrophages from SEMA7A shRNA knockdown mammary tumor bearers have decreased production of angiogenic chemokines CXCL2/MIP-2 and CXCL1 as well as matrix degrading enzyme, MMP-9." (PMID 24550834, 2014). "The MMP-9:TIMP-1 complex was measured with ELISA and with PLA in plasma samples obtained preoperatively from 465 breast cancer patients." (PMID 24330623, 2013). "In malignancies, TSP-1 suppressed MMP-9 activation in breast cancer, and TSP-1 expression negatively and significantly correlated with MMP-9 expression in human UC tissues." (PMID 23749112, 2013). "In fact, studies showed that inactivation of NFκB in MDA-MB-231 breast cancer cells inhibit the expression of many downstream target genes involved in tumor metastasis such as MMP-2, MMP-9, VEGF, ICAM-1 and uPAR." (PMID 23874773, 2013). "Particularly in breast cancer, MMP2 and MMP9 have been shown to play a major role in cell migration and invasion and their enhanced levels in patients predicts poor clinical prognosis." (PMID 24098477, 2013). "Twist protein expression was detected in 151 (75.5%) of the breast cancer tissues, while the expression of MMP-2 and MMP-9 were detected in 194 (97.0%) and 192 (96.0%) specimens." (PMID 23935727, 2013). "As shown in breast cancer cells, TGF-β1 strongly induced the expression and activation of MMP-2 and MMP-9; those inductions were dose-dependently inhibited by CX-4945." (PMID 24023938, 2013). "Previous studies have suggested that matrix metalloproteinases (MMP-2 and MMP-9) and their inhibitors (TIMP-1 and TIMP-2) play important roles in the invasion and metastasis of breast cancer." (PMID 23935727, 2013). "majorana inhibits breast cancer cell invasion by affecting the expression of MMP-2 and MMP-9, we decided to examine the protein expression level of MMP-2 and MMP-9 in the conditioned medium using OME-treated MDA-MB-231 cells." (PMID 23874773, 2013).
breast carcinoma (continued). "In breast cancer and melanoma cells, miR-340 and miR-34a lowered c-Met (an inducer of MMP-2 and MMP-9) and, thus, suppressed tumor cell migration and invasion." (PMID 23325049, 2013). "Because breast cancer and lung cancer WT cells are already expressing MMP-2 and MMP-9, and assuming RNA levels translates into active protein levels, these cells should be primed for invasion but they are not." (PMID 24324647, 2013). "We developed a prognostic tool for early breast cancer based on the analysis of the relative expression level of FGF18, BCL2, PRC1, MMP9 and SERF1A in combination." (PMID 23648477, 2013). "To gain information on how ERK1/2 can mediate its effect on breast cancer cell migration and invasion, we next investigated and demonstrated that WNT‐5A signaling and constitutively active Cdc42 both decreased matrix metalloproteinase 9 (MMP9) activity." (PMID 23727359, 2013). "Rab27A has effects on the invasive and metastatic potentials of breast cancer cells by modulating the secretion of IGF-II, which regulates the expression of p16, VEGF, uPA, cathepsin D, cyclin D1, and MMP-9." (PMID 23977139, 2013). "The inhibition of STAT3 by LLL12 also down-regulated the expression of known STAT3 target genes in ALDH+ breast cancer cells related to cancer cell proliferation, survival, and angiogenesis, including Cyclin D1, survivin, Bcl-2, Bcl-XL, MMP-2, and MMP-9." (PMID 24376586, 2013). "MMP-9 is one of the most complex members of the MMP family and expression of MMP-9 is up-regulated in breast cancer." (PMID 23696797, 2013). "Despite earlier reports linking MMP-9 and TIMP-1 with prognosis in breast cancer patients, we here demonstrate that plasma levels of the MMP-9:TIMP-1 protein complex hold no prognostic information in primary breast cancer as a stand-alone marker." (PMID 24330623, 2013). "Cyclopamine also inhibited the invasive ability of both breast cancer cell lines by suppressing the expression levels of NF-κB, MMP2 and MMP9 protein." (PMID 23599805, 2013). "In this study, we report that WNT‐5A‐mediated activation of Cdc42 leads to decreased breast cancer cell migration and invasion via reduced ERK1/2 and MMP‐9 activities." (PMID 23727359, 2013). "Our results indicate that the downregulation of MMP9 mRNA and protein expression with naked anti-MMP-9 DNAzyme is sufficient to reduce mammary tumor burden." (PMID 23407024, 2013). "Thus, STAT3 may promote the progression of breast cancer through the regulation on MMP-9." (PMID 22179587, 2012). "The ERα coregulator (AIB1) amplified in breast cancer has been shown to promote breast cancer metastasis by activation of PEA3-mediated matrix metalloproteinase 2 (MMP2) and MMP9 expression." (PMID 22295247, 2012). "Kim and collaborators suggested that TGF-β1 also induces invasion in pre-malignant breast cancer cells (MCF10A), by upregulation of MMP-2 and MMP-9." (PMID 22260435, 2012). "Taken together, the results obtained demonstrate that TGF-β1 is a common regulator of MMPs (MMP-2 and MMP-9) and their inhibitors (TIMP-2 and RECK) in breast cancer cell models." (PMID 22260435, 2012). "Recently, one report showed that Rab27a affects the invasive and metastatic potential of breast cancer cells by modulating the secretion of IGF-II, which regulates the expression of p16, VEGF, uPA, cathepsin D, cyclin D1, and MMP-9." (PMID 23029308, 2012). "In regards to the role of TSP-1 in regulating MMP-9 in cancer cells, there were several opinions that TSP-1 acts as an inhibitor in breast cancer and ovarian cancer." (PMID 22928942, 2012). "The suppression of CD147 in breast cancer cells inhibited MMP2 and MMP9 production and cell invasion in vitro, while the invasive properties conferred on inflammatory cells by CypA are a result of MMP9 stimulation." (PMID 23031673, 2012).